LINGO4 (leucine rich repeat and Ig domain containing 4)
Synonyms: LRRN6D; DAAT9248; PRO34002
Tractability: Antibody: UniProt predicts a signal peptide or a membrane-spanning region; its Gene Ontology location is reachable by antibodies, with medium confidence.
Gene: Protein-coding gene on chromosome 1 (151,800,264 to 151,805,419, reverse strand). Ensembl gene ENSG00000213171.
Subcellular location: Membrane
Subcellular location (Human Protein Atlas): Golgi apparatus; Vesicles
Gene Ontology:
Molecular function: signaling receptor activity
Cellular component: plasma membrane; membrane
Genetic constraint (gnomAD): Loss-of-function variants: 22 observed, 27.63 expected, observed/expected ratio (o/e) 0.8, 90% interval 0.57 to 1.14. The upper end of that interval is the gene's LOEUF score, 1.14, which puts it in group 4 of 6, group 1 being the genes least tolerant of losing a copy. Missense variants: 706 observed, 764.82 expected, observed/expected ratio (o/e) 0.92, 90% interval 0.87 to 0.98. Synonymous variants: 306 observed, 340.2 expected, observed/expected ratio (o/e) 0.9, 90% interval 0.82 to 0.99.
Homologues: Orthologues: chimpanzee LINGO4 (99% identical), macaque LINGO4 (98% identical), mouse Lingo4 (94% identical), pig LINGO4 (94% identical), rat Lingo4 (93% identical), dog LINGO4 (93% identical), rabbit LINGO4 (92% identical), guinea pig LINGO4 (91% identical), zebrafish lingo3a (42% identical), tropical clawed frog lingo3 (41% identical), Drosophila melanogaster CG5819 (18% identical), zebrafish lrtm2b (15% identical), and 5 more. Paralogues in human: LINGO3 (43% identical), ECM2 (14% identical), LUM (14% identical), FMOD (13% identical), OMD (12% identical), PRELP (11% identical), KERA (11% identical), EPYC (11% identical), OMG (10% identical), OGN (9% identical).
Diseases named in the same sentence as LINGO4 in open-access papers:
LINGO4 is named in the same sentence as 3 diseases in open-access papers, as found by Europe PMC text mining. Sharing a sentence is not in itself a finding about the gene and the disease. The quoted sentences say what the papers report.
insomnia (1 paper, 2025). A sleep disorder characterized by difficulty in falling asleep and/or remaining asleep. "Interestingly, of 554 risk loci for insomnia identified thus far, this locus is among only three loci that colocalize with CVD (pp>0.90; others include the APOE region and LINGO4/RORC)." (PMID 40176577, 2025).
rhabdoid tumor (1 paper, 2022). An aggressive malignant embryonal neoplasm usually occurring during childhood. "The two samples in this case, of the kidney and abdomen, were determined to share a single tumorigenic origin on the basis of shared SNVs in MST1 and LINGO4, in addition to the chr22 LOH event often observed in rhabdoid tumors." (PMID 35912263, 2022).
LINGO4 also shares sentences with these, for which no sentence is quoted: essential tremor (1 paper).